BRAF (B-Raf proto-oncogene, serine/threonine kinase)
Diseases named in the same sentence as BRAF in open-access papers (continued):
Sharing a sentence is not in itself a finding about the gene and the disease.
metastatic melanoma (continued). "Trametinib is FDA-approved for the treatment of human patients with unresectable or metastatic melanoma harboring BRAF (v-raf murine sarcoma viral oncogene homolog B1) V600E or V600K mutations." (PMID 36590793, 2022). "Encorafenib (LGX818, trade name Braftovi) is a novel anticancer agent that has been recently approved for the clinical management of unresectable or metastatic melanoma and metastatic colorectal cancer with BRAF mutations." (PMID 36559089, 2022). "We report the case of a 71-year-old female patient with metastatic melanoma harboring a BRAF-V600E mutation undergoing targeted therapy with dabrafenib and trametinib." (PMID 35454350, 2022). "Private health insurance in Brazil must cover BRAF and MEK inhibitors for patients with either resected high-risk or metastatic melanoma harboring BRAF V600E or V600K mutations." (PMID 36589179, 2022). "In this retrospective, single-center, real-world analysis, we identified 135 patients with BRAF-mutated, metastatic melanoma who received consecutive treatment with TT followed by CPI, or vice versa, as first and second-line therapy, respectively." (PMID 35565212, 2022). "Dabrafenib plus trametinib combination therapy is routinely used as a TT and was licensed for use in metastatic melanoma with BRAF V600E or V600K mutations in August 2015." (PMID 35559986, 2022). "Mutations on BRAF, in particular V600 mutations, are associated with poor prognosis in some cancers such as metastatic melanoma." (PMID 36358912, 2022). "This study led to the approval of this combination therapy for BRAF-mutated unresectable or metastatic melanoma." (PMID 35453572, 2022). "The AC recommended Enco + Bini for the treatment of adult patients with unresectable or metastatic melanoma with a BRAF V600 mutation." (PMID 32291725, 2021). "Targeting the MAPK signaling pathway has significantly improved the treatment of metastatic melanoma, with BRAF mutations being the most frequent and most important alterations to be treated." (PMID 34571969, 2021). "A phase three randomised clinical trial compared vemurafenib with chemotherapy dacarbazine in 675 previously untreated subjects having metastatic melanoma with the BRAF V600E mutation." (PMID 34441278, 2021). "The azetidine-containing cobimetinib (GDC-0973, RG7420) is a MEK inhibitor by Exelixis and Genentech (Roche) approved by the FDA and EMA in 2015 for the treatment of metastatic melanoma expressing BRAF V600E or V600K mutation as a combination with vemurafenib." (PMID 34885651, 2021). "The NICE AC recommended Enco + Bini as a first-line treatment for unresectable or metastatic melanoma with a BRAF V600 mutation." (PMID 32291725, 2021). "Vemurafenib and trametinib have a lot of successful experiences in the treatment of unresectable or metastatic melanoma with BRAF V600E mutation." (PMID 35145907, 2021). "BRAF inhibitors (e.g., vemurafenib) are widely used to treat metastatic melanoma with the BRAF V600E mutation." (PMID 33840166, 2021). "Our results revealed for the first time that the upregulation of PLA1A in the serum of advanced metastatic melanoma tissues represent an excellent diagnostic marker in BRAF/NRAS-driven melanomagenesis." (PMID 33723350, 2021). "Therapies targeting RAF/MEK/ERK expression and/or signaling have been approved for the treatment of unresectable or metastatic melanoma associated with BRAF V600E or V600K mutations." (PMID 34588427, 2021). "For patients with metastatic melanoma, a rapid BRAF mutation assessment is vital to reveal the treatment options per patient." (PMID 34359813, 2021). "Encorafenib is for unresectable or metastatic melanoma patients with BRAF V600E or BRAF V600K mutation and treat metastatic colorectal cancer (mCRC) patients with BRAF V600E mutation (combined with cetuximab)." (PMID 34976824, 2021).
metastatic melanoma (continued). "The results of the retrospective analysis demonstrated that TT was well tolerated and controlled in patients with BRAF V600 mutation-positive unresectable or metastatic melanoma in a real-world setting." (PMID 34064013, 2021). "Recently, a clinical trial evaluating dabrafenib (300 mg twice daily), trametinib (2 mg once daily), and pembrolizumab (2 mg/kg every 3 weeks) was conducted in 60 patients with BRAF V600E/K-mutated metastatic melanoma." (PMID 33868987, 2021). "Median age at time of metastatic melanoma diagnosis was 66 years (range: 21–86), 60 (52%) were female, and 64 (55%) had a BRAF‐mutation." (PMID 34741440, 2021). "Targeted therapies such as BRAF inhibitors (BRAFi) initially showed great promise in patients with BRAF(V600)‐mutated metastatic melanoma." (PMID 33724679, 2021). "Patients with BRAF V600E–mutated metastatic melanoma respond well to BRAF inhibitors; however, BRAF V600E–mutated mCRC patients respond relatively poorly (only 5%)." (PMID 34868987, 2021). "We report the case of a young woman who developed metastatic melanoma in the inguinal nodal region, which acquired chondrosarcomatous differentiation and preserved the BRAF mutation found in the primary tumor." (PMID 33936664, 2021). "This multicenter retrospective study included patients with BRAF V600-mutated irresectable AJCC-v8 stage IIIC/D to IV metastatic melanoma who received treatment with vemurafenib (VEM) or vemurafenib plus cobimetinib (COBIVEM)." (PMID 34109122, 2021). "Patients with BRAF mutated (BRAF-mt) metastatic melanoma benefit significantly from treatment with BRAF inhibitors." (PMID 33915880, 2021). "We showed that sustained activation of AhR induces the expression of genes associated with resistance to BRAF inhibitors in the treatment of metastatic melanoma." (PMID 33451095, 2021). "Targeting BRAF V600‐mutant tumors with selective BRAF and MEK inhibitors is the current standard treatment for patients with metastatic melanoma, in which the BRAF V600E mutation is more common than in NSCLC." (PMID 33215864, 2021). "For patients with newly diagnosed metastatic melanoma, rapid BRAF mutation (mBRAF) assessment is vital to promptly initiate systemic therapy." (PMID 34359813, 2021). "BRAF mutations are present in 40–60% of primary and metastatic melanomas (of which on average 80% carry the BRAFV600E variant) and are important for cell proliferation and resistance to apoptosis." (PMID 34831017, 2021). "In 2013, dabrafenib (Tafinlar®) was approved as a single agent for treatment of unresectable or metastatic melanoma with BRAF V600E mutation." (PMID 34771633, 2021). "The aim of this prospective study was to confirm the clinical validity of circulating tumor DNA (ctDNA) for minimally invasive BRAF mutation testing and treatment monitoring of metastatic melanoma patients with elevated lactose dehydrogenase serum levels." (PMID 34359813, 2021). "Trametinib (Mekinist®) is indicated as monotherapy or combinational therapy for the treatment of patients with unresectable or metastatic melanoma with a BRAF V600 mutation." (PMID 34771633, 2021). "Trametinib as monotherapy or in combination with dabrafenib is indicated for the treatment of adult patients with unresectable or metastatic melanoma with a BRAF V600 mutation (see sections 4.4 and 5.1)." (PMID 34790681, 2021). "The medical treatment of metastatic melanoma (MM) has recently been significantly improved by the identification of specific genetic alterations, such as BRAF, NRAS and cKIT mutations." (PMID 33530579, 2021). "Combined BRAF (BRAFi) and MEK inhibitors (MEKi) are now the recommended first line for BRAF mutated Metastatic Melanoma (MM)." (PMID 34207200, 2021).
metastatic melanoma (continued). "The FDA approved trametinib for the treatment of patients with unresectable or metastatic melanoma with BRAF V600E/K mutations as a single agent in 2013 and in combination with dabrafenib (Tafinlar®) in 2014." (PMID 34771633, 2021). "Binimetinib in combination with encorafenib is indicated for the treatment of adult patients with unresectable or metastatic melanoma with a BRAF V600 mutation (see sections 4.4 and 5.1)." (PMID 34790681, 2021). "The recent 5-year pooled analysis including 563 treatment- naïve patients with BRAF V600E/K mutated, unresectable or metastatic melanoma were randomly assigned to receive either D + T or D plus placebo or vemurafenib (V)." (PMID 33801689, 2021). "Trametinib, which is an MAPK inhibitor, is used for to treat patients with unresectable or metastatic melanoma carrying the BRAF V600E mutation." (PMID 34925303, 2021). "Before taking encorafenib, patients must have unresectable or metastatic melanoma with BRAF V600 mutation or metastatic colorectal cancer with BRAF V600E mutation confirmed by a validated test." (PMID 34790681, 2021). "Due to the therapeutic consequences, determination of the BRAF mutation status in patients with metastatic melanoma is mandatory according to the European Society of Medical Oncology guidelines." (PMID 33915880, 2021). "It is well known that approximately 50% of metastatic melanomas harbor BRAF oncogene mutations, which lead to the uncontrolled activation of the mitogen-activated protein kinase (MAPK) signaling pathway." (PMID 33498201, 2021). "Instead focusing on BRAF-mutant metastatic melanoma patients Kolenda and colleagues evaluated the associations between the expression levels of lncRNAs and patients’ responses to vemurafenib treatment." (PMID 33503876, 2021). "BRAFi provokes tumor shrinkage in the vast majority of patients with BRAF(V600)‐mutated metastatic melanoma but resistance almost inevitably occurs." (PMID 33724679, 2021). "The first-line therapy for patients with metastatic melanoma (MM) with a BRAF V600E mutation is a BRAF inhibitor (BRAFi) such as vemurafenib." (PMID 34638245, 2021). "At the moment, a phase II clinical trial is testing the efficacy and safety of tazemetostat in combination with dual BRAF/MEK inhibition in patients with BRAF-mutated metastatic melanoma who progressed on prior BRAF/MEKi therapy (NCT04557956)." (PMID 34575678, 2021). "In 2014 it was approved for use in combination with trametinib (MEK1/2 inhibitor) which was also FDA-approved in 2013 to treat patients with unresectable or metastatic melanoma with a BRAF V600E/K mutation." (PMID 34771633, 2021). "Immunomodulators and targeted agents against mutations in the BRAF gene have become established treatment for patients with metastatic melanoma, offering a survival benefit." (PMID 33993415, 2021). "The drug was first approved in August 2011 for the treatment of unresectable or metastatic melanoma associated with the BRAF V600 mutation." (PMID 34298662, 2021). "This retrospective study collected data from 43 patients with BRAF V600E/K mutation-positive metastatic melanoma from a single Chinese cancer center." (PMID 33868987, 2021). "In almost fifty percent of patients with metastatic melanomas, valine is replaced with glutamine in codon 600 of the serine/threonine kinase BRAF (BRAF V600 mutation)." (PMID 34065883, 2021). "Mutations in the BRAF (v-Raf murine sarcoma viral oncogene homolog B) oncogene are observed in ~50% of metastatic melanomas, with over 90% of those mutations resulting in a glutamic acid–valine substitution at codon 600 (BRAF V600E)." (PMID 33920605, 2021). "This possibly explains why therapies targeting mutant BRAF (a driver mutation already present in the pre-malignant cutaneous nevus) have been so successful in the treatment of metastatic melanoma." (PMID 33588787, 2021).
metastatic melanoma (continued). "Encorafenib in combination with binimetinib is indicated for the treatment of adult patients with unresectable or metastatic melanoma with a BRAF V600 mutation (see sections 4.4 and 5.1)." (PMID 34790681, 2021). "These treatment options are of particular importance, as 40% to 60% of metastatic melanomas harbor the BRAF mutation." (PMID 37632820, 2021). "In daily practice, the BRAF V600E mutation is best known, for example in patients with metastatic melanoma who respond very well to BRAF/MEK inhibitors." (PMID 33799327, 2021). "Cotellic is indicated for use in combination with vemurafenib for the treatment of adult patients with unresectable or metastatic melanoma with a BRAF V600 mutation (see sections 4.4 and 5.1)." (PMID 34790681, 2021). "There was only one published cost-effectiveness comparison between dabrafenib plus trametinib and vemurafenib as a first-line treatment in patients with BRAF V600 mutation-positive unresectable or metastatic melanoma, which was in a Swiss setting." (PMID 34201096, 2021). "The aim of this study was to evaluate the utility of CT-based radiomics to predict BRAF mutation status (mutant versus wild type) in metastatic melanoma." (PMID 33915880, 2021). "Trametinib is a selective and highly potent small molecule inhibitor of MEK1/2 with high oral bioavailability currently approved by the FDA for the treatment of unresectable or metastatic melanoma with BRAF V600E or V600K mutations." (PMID 34588427, 2021). "Encorafenib is licensed in Europe for use in combination with binimetinib, for the treatment of patients with BRAF V600 mutation-positive unresectable or metastatic melanoma." (PMID 32291725, 2021). "Benzo[d]imidazole-based binimetinib (Mektovi, ARRY-162) is a MEK1/2 inhibitor approved in 2018 for the treatment of unresectable or metastatic melanoma with BRAF mutations, in association with encorafenib, a MAPK inhibitor." (PMID 34885651, 2021). "No new safety or efficacy concerns were observed in this interim PMS analysis in Japanese patients with unresectable and metastatic melanoma with BRAF gene mutation who received dabrafenib and trametinib combination therapy." (PMID 32699976, 2020). "The phase I/II trial demonstrated the safety of dabrafenib and trametinib combination and its significant superiority in terms of ORR and PFS over dabrafenib monotherapy, among patients with BRAF V600E/K-mutated, unresectable or metastatic melanoma." (PMID 32760738, 2020). "Targeted therapy, mostly represented by BRAF inhibitors, shows efficacy in the treatment of BRAF mutated metastatic melanoma when administered as single agents or in combination with MEK inhibitors." (PMID 32948083, 2020). "In one study, 73% of 48 patients with metastatic melanoma had tumor-associated BRAF and NRAS alterations in ctDNA analysis." (PMID 32010431, 2020). "BRAF inhibitors (BRAFi), which are usually used in combination with MEK inhibitors (MEKi), are important in the therapy of BRAF-mutated metastatic melanoma (MM)." (PMID 33081201, 2020). "In spite of that, the estimation of YRNAs appears to be a prognostic marker for BRAF-mutated metastatic melanoma patients and helps to assess progression free survival and overall survival." (PMID 32784396, 2020). "One study by Li et al33 compared the use of a single BRAF V600 variation test to a panel of 34 genes in the diagnostic workup for metastatic melanoma and found that the panel was less expensive and yielded more QALYs than the single-gene test." (PMID 32986105, 2020). "The aims of this study were to characterize the pharmacokinetics of DAB, hydroxy-dabrafenib (OHD), and TRA in BRAF-mutated patients and to investigate the exposure–response relationship for toxicity and efficacy in metastatic melanoma (MM) patients." (PMID 32283865, 2020). "Drug resistance severely limited the efficacy of target-based therapy in BRAF-mutated metastatic melanoma." (PMID 32013263, 2020).
metastatic melanoma (continued). "Mutations of the BRAF proto-oncogene, at the p.V600 codon, has been detected in more than 50% of primary and metastatic melanoma cells in clinical samples." (PMID 32754440, 2020). "In a more recent study, researchers used immunomagnetic beads for CTCs enrichment from metastatic melanoma patients blood with BRAF mutated tumors." (PMID 32695793, 2020). "In a pre-clinical model of AVM using BRAF-mutated zebrafish, treatment with the orally active inhibitor of mutated BRAF, vemurafenib, used clinically to treat BRAF-mutated metastatic melanoma, restores normal blood flow." (PMID 33634164, 2020). "BRAF inhibitors have revolutionized the treatment of V600E BRAF metastatic melanoma, but the rationale underlying the use of such inhibitors cannot explain a response in CRC patients because the molecular landscape is more complex and heterogeneous." (PMID 32899322, 2020). "Dabrafenib and trametinib as monotherapy or as combination therapy have been approved in the US and Europe for the indication of unresectable or metastatic melanoma with BRAF V600 mutations." (PMID 32699976, 2020). "Despite improved overall survival of patients with metastatic melanoma treated with an inhibitor to target BRAF mutation, cancer can rapidly acquire resistance to the treatment that limits its long-term efficacy." (PMID 32214200, 2020). "As a first line of treatment, BRAF inhibitors are indicated in combination with MEK inhibitors (MEKi) for patients with BRAF-mutated metastatic melanoma (40% of cases)." (PMID 32664549, 2020). "Most were newly indicated for the treatment of unresectable or metastatic melanoma with BRAF V600E or V600K mutations, as detected by FDA-approved tests in 2018." (PMID 33084582, 2020). "With regards to combination, a pilot study evaluated the combination of vemurafenib (BRAF inhibitor) with ACT in 11 patients with metastatic melanoma harboring BRAFV600E/K mutation." (PMID 32679922, 2020). "Here, for the first time, we determine the antitumor potential of tomatine, a mixture of α-tomatine and dehydrotomatine, in metastatic melanoma (MM) cell lines harboring different BRAF and MC1R variants." (PMID 32718103, 2020). "Vemurafenib is the first BRAF serine-threonine kinase protein inhibitor authorized for the treatment of adult patients with unresectable or metastatic melanoma with a BRAF V600E positive mutation." (PMID 32344898, 2020). "Target therapies based on BRAF and MEK inhibitors (MAPKi) have changed the therapeutic landscape for metastatic melanoma patients bearing mutations in the BRAF kinase." (PMID 32933538, 2020). "In the present meta-analysis, a correlation to the presence of BRAF mutations and the presence of metastatic melanomas was found." (PMID 31274706, 2020). "Combination therapy with Dabrafenib and Trametinib (Mekinist®), an MEK 1 and 2 inhibitor, produces superior response rate to BRAF inhibition alone and has been approved for metastatic melanoma with either BRAF V600E or V600K mutations." (PMID 31748891, 2020). "A recent study designed to identify factors associated with the treatment of metastatic melanoma in the United States found that older patients were less likely to receive ipilimumab or to be tested for the BRAF mutation." (PMID 33409455, 2020). "Concurrently, triple combination therapy inhibiting BRAF, ERK and PD1 in patients with BRAF V600-mutated metastatic melanoma displayed persistent antitumor response." (PMID 32793604, 2020). "In this study, we first developed a PDX library of BRAF-mutant metastatic melanoma, with accompanying DNA mutational profiling of key driver genes, as well as clinical annotation." (PMID 31857724, 2020). "Treatments of metastatic melanoma underwent an impressive development over the past few years, with the emergence of small molecule inhibitors targeting mutated proteins, such as BRAF, NRAS, or cKIT." (PMID 32455924, 2020).